VWF (von Willebrand factor)
Diseases named in the same sentence as VWF in open-access papers (continued):
Sharing a sentence is not in itself a finding about the gene and the disease.
Sepsis (106 papers, 2005 to 2026). Sepsis is defined as life-threatening organ dysfunction caused by a dysregulated host response to infection. "The release of vWF multimers in the context of sepsis-associated ADAMTS13 deficiency determines microvascular thrombosis with an impact on organ dysfunction severity." (PMID 36675530, 2023). "ADAMTS-13 deficiency, leading to ultra large von Willebrand factor multimers and thrombotic microangiopathy in sepsis, was associated with sepsis severity and poor prognosis." (PMID 36836706, 2023). "A previous study reported that patients with high VWF:Ag/ADAMTS13:AC levels had a high risk of sepsis with MOF." (PMID 36829443, 2023). "It has previously been reported that high plasma level of vWF was associated with a greater risk of developing ARDS in sepsis patients and was associated with higher mortality in patients with established ARDS." (PMID 29442256, 2018). "ISE pretreatment significantly decreased the increase in vWF caused by sepsis." (PMID 38921594, 2024). "Therefore, a new pathogenic entity in sepsis was defined as “endotheliopathy-associated vascular microthrombotic disease” involving microthrombosis mainly through unusually large vWF multimers." (PMID 35721048, 2022). "Reduced ADAMTS13 activity concomitant with increased plasma VWF levels has been observed in thrombotic microangiopathies (TMAs) associated with systemic inflammation, such as in severe sepsis, sepsis-induced disseminated intravascular coagulation (DIC), malignancy, and autoimmune diseases." (PMID 33343584, 2020). "In critically ill patients, sepsis-induced endotheliopathy is sometimes associated with vascular microthrombosis mediated by platelet activation and the endothelial release of von Willebrand factor (vWF) multimers, which in turn impairs O2 delivery to mitochondria." (PMID 38811967, 2024). "However, the pathological significance of vWF-integrin αvβ3 interactions in sepsis-associated endothelial hyperpermeability and the underlying molecular mechanism remain unclear." (PMID 38921594, 2024). "Sepsis disrupts the delicate balance between vWF and the enzyme known as a disintegrin and metalloproteinase with thrombospondin type 1 motif 13 (ADAMTS13), leading to lower ADAMTS13 activity in a background of elevated vWF levels." (PMID 40003683, 2025). "Another factor leading to TP is excessive platelet activation triggered by elevated levels of von Willebrand factor (VWF), resulting from acquired ADAMTS-13 deficiency, a common finding in sepsis." (PMID 41306494, 2025). "Increased von Willebrand factor (vWF) plasma levels, stemming from activated platelets and endothelium injury during sepsis, can bind to integrin αvβ3, exacerbating endothelial permeability." (PMID 38921594, 2024). "For a more intuitive observation, we used immunofluorescence to observe the effect of ISE on vWF derived from sepsis lung ECs." (PMID 38921594, 2024). "In our study, the patients with a high probability of sepsis showed a mean of 674% vWF activity, which is similar to what has been reported in previous studies." (PMID 39200994, 2024). "Our previous research revealed that ISE specifically inhibits platelet activation and release with a relatively low IC50 value, suggesting that ISE affects vWF released from activated platelets during sepsis." (PMID 38921594, 2024). "Here, we observed increased vWF in sepsis-induced lung sections, which was significantly reduced by ISE." (PMID 38921594, 2024). "ISE also significantly reduced the increased release of vWF from activated platelets and platelet–EC interaction during sepsis." (PMID 38921594, 2024). "In critical illnesses such as trauma, sepsis, and burns, plasma vWF significantly increases and is accompanied by a concomitant decrease in ADAMTS13 (a disintegrin and metalloprotease with thrombospondin type-1 repeats 13) activity." (PMID 39200994, 2024).
Sepsis (continued). "VWF in sepsis represents another component of “immunothrombosis”, as VWF interacts with NETs by electrostatic forces, further inducing the vicious cycle of inflammation and thrombosis." (PMID 37886991, 2023). "Similar to fibrinogen, FVIII and VWF levels are elevated in sepsis, as they also serve as acute-phase reactants." (PMID 37886991, 2023). "Plasma samples from all sepsis cases also displayed an increase in vWF concentration as well as differences in the concentrations of factors VII, V, prothrombin, and thrombomodulin." (PMID 36829233, 2023). "Mean plasma concentrations of all endothelial and inflammatory biomarkers, except vWF, were higher in the sepsis cohort than in controls." (PMID 37520007, 2023). "Additional studies have shown that VWF and ADAMTS-13 levels are clearly associated with disease severity and/or poor prognosis in sepsis." (PMID 37886991, 2023). "Prior studies have described a role for ADAMTS13, a protein responsible for the cleavage of VWF multimers, in sepsis." (PMID 37159776, 2023). "ADAMTS13 becomes inactivated during sepsis, resulting in incomplete VWF cleavage, thereby increasing blood viscosity and stasis." (PMID 37159776, 2023). "Certain studies, similarly to ours, have demonstrated the persistence of high VWF levels during the course of sepsis, particularly in patients with the worst outcomes." (PMID 37886991, 2023). "ADAMTS-13 levels in sepsis have been measured at around 20–43% of normal levels and an imbalance in the VWF/ADAMTS-13 system is observed under inflammatory conditions." (PMID 37886991, 2023). "Both vWF and TM are markers of endothelial cell activation and their levels are elevated during sepsis (López-Aguirre and Páramo, 1999)." (PMID 36408247, 2022). "Consequentially, an increased vWF:Ag/ADAMTS13 ratio has been repeatedly associated with severity of shock and organ failure as well as increased mortality in sepsis." (PMID 35551628, 2022). "Consistent with the results of previous studies, plasma von Willebrand factor antigen (VWF) levels were significantly higher in ALI/ARDS sepsis patients, and the plasma level of VWF was independently related to mortality." (PMID 35668098, 2022). "Pathogen-induced sepsis activates the complement system leading to generalized endotheliopathy, which releases ultra large von Willebrand factor (ULVWF) multimers from ECs and promotes ULVWF path of hemostasis." (PMID 35207507, 2022). "Hemostatic changes in ACLF and sepsis greatly overlap: they are both associated with elevated levels of VWF, D-dimer, factor VIII, thrombin-antithrombin and decreased levels of the VWF-regulating protease ADAMTS13 and coagulation factors." (PMID 35223914, 2022). "The functional aspects of S. aureus binding to vWF can be correlated with the pathophysiological consequences of this interaction such as infective endocarditis, sepsis, and cardiovascular complications." (PMID 34815454, 2021). "Longitudinal changes in the activity and antigen levels of ADAMTS13 and VWF throughout the course of sepsis still remain poorly characterized." (PMID 33606732, 2021). "In sepsis, elevated VWF antigen and activity can be accompanied by reductions in the ADAMTS13 metalloproteinase responsible for cleaving ultra-large VWF multimers into smaller VWF forms." (PMID 33058027, 2021). "Younger adults expressed fibrinogen, and von Willebrand factor in response to sepsis while CRP, LBP, and A1ACT showed lower concentrations in older adults who developed severe sepsis but Apo M in older adults was associated with increased mortality." (PMID 32636717, 2020). "The level of vWF was negatively correlated with mean platelet counts, confirming that vWF localises platelets to the endothelial surface in sepsis." (PMID 31803186, 2019). "In the adverse outcome group, it was thought that the immune system was activated until the end, strongly suggesting that vWF propolypeptide plays a role in host defense in sepsis." (PMID 31568522, 2019).
Sepsis (continued). "VWF is released in high amounts during stress, inflammation, sepsis, and cardiovascular diseases and is also regarded as an indicator of vascular dysfunction." (PMID 30972039, 2019). "Sepsis results in a pro-thrombotic state with increases in plasma tissue factor and von Willebrand factor levels." (PMID 31484576, 2019). "Plasma vWF is reported to be more active in infants than in adults, and vWF can be the first haematological sign of sepsis." (PMID 31803186, 2019). "In this view, it is interesting to observe how in clinical studies on patients with SIRS and sepsis, VWF and ADAMTS13 have shown to be a prognostic biomarker identifying patients with worse outcome and a higher risk of death." (PMID 28634421, 2017). "In ongoing in vitro studies, this research group has found that ApoA1 can potently inhibit VWF self-association and consequent platelet accumulation, and has also shown that in sepsis, ApoA1 levels correlate inversely with total active VWF." (PMID 26830467, 2016). "For example, in some cases of severe sepsis, attenuation in the release of ADAMTS13 results in the formation of large vWF multimers causing disseminated microvascular thrombosis and organ failure." (PMID 24408224, 2014). "In patients, circulating Ang-2, VEGF, and von Willebrand factor (VWF) levels are increased during ALI/ARDS or sepsis." (PMID 25178399, 2014). "Beside coagulation disturbances, abnormalities of von Willebrand factor (VWF), related to endothelial damage, have been reported in sepsis patients during the last decade." (PMID 24238574, 2013). "Eight studies examined the capability of circulating vWF levels to differentiate patients with sepsis from patients with other illnesses." (PMID 22248019, 2012). "Reduced concentrations of the protein, leading to increased circulating levels of ultra-large von Willebrand factor (ULVWF) have been shown in a subset of patients with sepsis." (PMID 22206706, 2011). "Because our results suggest that impaired endothelial NO bioavailability exacerbates WPB release, they provide a plausible explanation for the increase in both Ang-2 and vWF in patients with sepsis." (PMID 20482750, 2010). "Secondly, in the process of endothelial cell injury and apoptosis induced by sepsis, von Willebrand factor (vWF), expressed during these events, further enhances platelet activation and aggregation through glycoprotein receptors (GPVI and GPIbα--IX-V) on the platelet membrane." (PMID 40103585, 2025). "More recently, in a murine model of sepsis induced by caecal ligation and puncture (CLP), a study from our group demonstrated the protective effects of isaridin E against sepsis through the suppression of von Willebrand factor (vWF)-mediated platelet–endothelial interactions." (PMID 40278266, 2025). "We therefore examined whether ISE regulates the release of vWF from platelets and ECs during sepsis." (PMID 38921594, 2024). "Elevated platelet counts or elevated procoagulant acute phase reactants e.g., fibrinogen, factor VIII, and or von Willebrand factor, in response to sepsis, DIC, CoViD, H1N1, etc. may also lead to HR as measured by aPTT." (PMID 39303137, 2024). "Overall, these results suggest that ISE may reduce locally high accumulation of vWF by decreasing its secretion from activated platelets and injured ECs during sepsis." (PMID 38921594, 2024). "Markers of endothelial cell damage, such as vWF and TM, are elevated in sepsis." (PMID 37159591, 2023). "ADAMTS-13 activity has been found to be decreased in patients with sepsis, which may increase platelet-vessel wall interaction by an increased presence of ultra-large VWF multimers." (PMID 38034541, 2023). "We found that RBC transfusion is associated with an increase in circulating vWF antigen levels, independent of the presence of sepsis or organ injury level of the patient." (PMID 34196412, 2022).
Sepsis (continued). "RBC transfusion in critically ill patients was associated with an increase in circulating vWF levels, suggesting a further increase in activation of the endothelium, a finding that was independent of the presence of sepsis or organ injury level." (PMID 34196412, 2022). "Sepsis results in overexpressed vWF from ECs and a decreased availability of ADAMTS13." (PMID 35721048, 2022). "Further, the past medical literature suggested CVST was associated with head injury, and the consistent laboratory findings in both vaccine-induced CVST and sepsis-associated VTE were characterized by increased FVIII activity and overexpression of VWF confirming of an underlying endotheliopathy." (PMID 35207507, 2022). "The persistent abnormalities in ADAMTS13 and VWF in sepsis patients discharged from the ICU may contribute to a sustained prothrombotic state." (PMID 33606732, 2021). "Mounting VWF/ADAMTS13 imbalance, culminating in the accumulation of uncleaved VWF molecules has been shown to increases the risk of developing secondary thrombotic microangiopathy in sepsis." (PMID 33058027, 2021). "CFD and VWF are important biomarkers of acute mortality for severe sepsis." (PMID 32174955, 2020). "Collectively, the results suggest that the plasma vWF level may serve as an early indicator of sepsis as well as the immunomodulatory effects of early colostrum feeding." (PMID 31803186, 2019). "For example, increased circulating numbers of EC and higher levels of soluble markers of EC activation/damage [e.g., intercellular adhesion molecule 1, von Willebrand factor, vascular endothelial (VE) growth factor receptor 1] correlate with more severe sepsis and higher mortality." (PMID 30116240, 2018). "In addition, increased numbers of circulating EC and soluble markers of EC damage (e.g., intercellular adhesion molecule 1, von Willebrand factor [vWF], and vascular endothelial growth factor receptor 1) correlate with more severe sepsis and higher mortality." (PMID 28250575, 2017). "In a single-center observational study of 40 patients conducted as part of a larger randomized-controlled trial of C1-inhitbitor supplementation in all-cause sepsis they show that ADAMST13 levels were lower and VWF antigen levels were higher in severe sepsis or septic shock." (PMID 28296884, 2017). "Moreover, in a mouse model of sepsis, VWF secretion was a major determinant of ADAMTS-13 decrease and played an important role in sepsis-induced mortality." (PMID 28775254, 2017). "We note, incidentally, that other additional mechanisms may contribute to the accumulation of VWF during sepsis: for example, oxidative modification of VWF in sepsis has been shown to prevent cleavage of VWF by ADAMST13." (PMID 28296884, 2017). "In the normal state, circulating proteases, notably ADAMTS13, degrade vWF into smaller multimers thereby reducing the thrombogenic propensity of vWF; however, in sepsis this homeostatic function may go awry." (PMID 24408224, 2014). "As a consequence of its implication on VWF multimer synthesis, sepsis has been reported as one of the factors that might trigger thrombotic microangiopathy and TTP is one of the differential diagnoses of DIC." (PMID 24238574, 2013). "As elevated levels of vWF are observed in several inflammatory disease states including sepsis, it is believed that normal or mildly reduced levels of ADAMTS-13 activity may not be sufficient enough to control vWF multimer size." (PMID 23537039, 2013). "Two other studies found a significant correlation between VWF and sepsis severity." (PMID 22248019, 2012). "Furthermore, plasma vWF is raised in proportion to plasma Ang-2 in patients with sepsis and acute lung injury." (PMID 20482750, 2010). "Our study indicates that the vWF/ADAMTS13 ratio may have potential as a surrogate marker of sepsis." (PMID 39200994, 2024).
Sepsis (continued). "Also, the use of some of these biomarkers could be a feasible discriminating tool for the differential diagnosis between CAR T-cell-related severe toxicities and sepsis (Ang-2, NETs, sC5b-9, VWF antigen, and PAI-1 antigen)." (PMID 38034541, 2023). "Additionally, VWF was found to directly bind to DNA in neutrophil extracellular traps (NETs) via specific arginine residues in its A1 domain, indicating a role of VWF in sepsis and pathogen defense." (PMID 34572000, 2021). "A change in VWFpp:Ag ratio would indeed be predicted to occur when changes in VWF homeostasis occur over hours to days, and this scenario as has been proposed to explain in the shift in the VWFpp:Ag ratio observed during acute illnesses, such as malaria and sepsis." (PMID 25409031, 2014). "In sepsis, ECs become activated, leading to an increase in the expression of various adhesion molecules such as ICAM-1, VCAM-1, E-selectin, P-selectin, and vWF." (PMID 39974277, 2025). "Sepsis is characterized by decreased ADAMTS-13 activity, which results in increased thrombogenic ultra-large von Willebrand factor (ULvWF) multimers and potentially diffuse microcirculatory platelet thrombosis." (PMID 38178170, 2024). "Nevertheless, our study is unique in that we compared the ISI with other markers of sepsis, including the MDW, serum lactate level, and vWF/ADAMTS13 ratio, which provides mechanistic insight into the various biomarkers used for assessing sepsis." (PMID 39200994, 2024). "Endothelial vWF and ADAMTS13 are important regulators of hemostasis, but their dysregulation during sepsis remains poorly studied." (PMID 39200994, 2024). "The findings indicate that IntelliSep, combined with plasma vWF/ADAMTS13 ratio, holds promise for enhancing early sepsis detection and treatment in emergency scenarios." (PMID 39200994, 2024). "As a result, we also measured the plasma levels of vWF and ADAMTS13 antigen in these patients and correlated these biomarkers with the sepsis score and IntelliSep ISI." (PMID 39200994, 2024). "In an in vitro experimental model of sepsis, there was progressive endothelial cell activation in correlation with the severity of sepsis, with significantly increased expression of surface adhesion receptors, such as ICAM-1, VCAM-1 and vWF, etc.." (PMID 37700349, 2023). "In contrast with other types of sepsis, an increase in the vWF/ADAMTS-13 ratio was observed, and a significant inverse correlation between vWF : Ag levels and ADAMTS-13 activity." (PMID 35719336, 2022). "The mechanism of ADAMTS13 dysregulation in sepsis is unknown, however it has been suggested to be a consequence of reduced synthesis, degradation by thrombin, consumption by massive amounts VWF, or impaired proteolytic activity in the presence of inflammatory mediators." (PMID 33606732, 2021). "Von Willebrand Factor (VWF) and ADAMTS13 are important regulators of hemostasis and their dysregulation during sepsis progression is not well understood." (PMID 33606732, 2021). "VWF, ADAMTS13 and platelets have been suggested as possible biomarkers for microangiopathic diseases such as sepsis." (PMID 28296884, 2017). "In some patients VWF and propeptide levels were even higher than the levels published in known cases of fulminant vascular disorders such as TTP and sepsis." (PMID 22125593, 2011). "Since the concentration of LPS in plasma or blood of patients with sepsis is about 200 ng/ml, we treated HUVEC with LPS (0.2 μg/ml) at different times (1, 2, 3, 8, 16, and 24 h) to determine VWF upregulation." (PMID 19171072, 2009). "During sepsis, immune cells interact with endothelial cells, inducing a pro-adhesive and pro-thrombotic phenotype rich of tissue factor (TF), E-selectin, ICAM-1, vascular cell adhesion molecule 1 (VCAM-1), and von Willebrand factor (vWF)." (PMID 38294676, 2024). "Next, they examined the role of the vWF and ADAMTS13 ratios in assessing the likelihood of sepsis." (PMID 39200994, 2024).